FXN (frataxin)
Diseases named in the same sentence as FXN in open-access papers (continued):
Sharing a sentence is not in itself a finding about the gene and the disease.
Friedreich ataxia (continued). "Several other transgenic mice carrying pathological frataxin gene alleles have yet to be tested for Friedreich ataxia phenotype." (PMID 26331028, 2014). "Friedreich's ataxia is an autosomal recessive degenerative disorder caused in most cases by a GAA triplet expansion in the FRDA gene encoding frataxin." (PMID 24116962, 2014). "Friedreich ataxia (FRDA) is a rare autosomal recessive neurodegenerative disorder caused by GAA repeat expansion mutation within intron 1 of the FXN gene, leading to decreased expression of the essential mitochondrial protein frataxin." (PMID 25538551, 2014). "Most individuals with Friedreich ataxia (FRDA) are homozygous for an expanded GAA triplet repeat (GAA-TR) mutation in intron 1 of the FXN gene, which results in deficiency of FXN transcript." (PMID 24737321, 2014). "Frataxin is a small mitochondrial protein whose reduced functional levels are associated with the development of Friedreich’s ataxia (FRDA), a neurodegenerative condition characterized by progressive ataxia and cardiomyopathy." (PMID 25333765, 2014). "Friedreich Ataxia is caused by an expanded GAA triplet repeat in the first intron of the frataxin gene, resulting in a 65–95% reduction in frataxin expression in Friedreich Ataxia patients." (PMID 25610371, 2014). "Friedreich ataxia is a progressive neurodegenerative disorder caused by GAA triplet repeat expansions or point mutations in the FXN gene and, ultimately, a deficiency in the levels of functional frataxin protein." (PMID 23691127, 2013). "Friedreich ataxia (FRDA) is an autosomal recessive neurodegenerative disorder caused by a GAA triplet repeat expansion or point mutations in the FXN gene." (PMID 23691127, 2013). "Friedreich’s ataxia (FA) is an autosomal recessive neurodegenerative disorder typically caused by trinucleotide expansion of GAA in the gene encoding frataxin." (PMID 23201762, 2012). "Human frataxin is the protein deficient in Friedreich ataxia (FRDA), a devastating autosomal recessive neurodegenerative disease associated with hypertophic cardiomyopthy, affecting 1/40,000 in the caucasian population." (PMID 21298097, 2011). "Friedreich ataxia (FRDA) is an autosomal recessive disorder caused by pathological GAA trinucleotide repeat expansions in the FXN gene (9q13-q21.1, OMIM 229300)." (PMID 21112411, 2011). "Friedreich's ataxia is an autosomal recessive neurodegenerative disease caused by a mutation in the FXN gene encoding the mitochondrial protein frataxin." (PMID 21776279, 2011). "Frataxin, the mitochondrial protein deficient in Friedreich ataxia, a rare autosomal recessive neurodegenerative disorder, is thought to be involved in multiple iron-dependent mitochondrial pathways." (PMID 21298097, 2011). "Friedreich's ataxia is a mitochondrial rare disease, which molecular origin is associated with a defect in the expression of frataxin." (PMID 21687738, 2011). "Friedreich's ataxia (FRDA) is caused by transcriptional repression of the nuclear FXN gene encoding the essential mitochondrial protein frataxin." (PMID 27721337, 2011). "The Drosophila fh gene is the ortholog of S. cerevisiae YFH1 and of human FXN, a gene associated with the neurodegenerative disorder Friedreich's ataxia." (PMID 20598113, 2010). "Expansion of an unstable GAA•TTC repeat in the first intron of the FXN gene causes Friedreich ataxia by reducing frataxin expression." (PMID 20559546, 2010). "We previously demonstrated that cells derived from Friedreich ataxia patients show signs of cytosolic iron deficiency, and that cellular frataxin mRNA levels were decreased after experimental induction of iron deficiency." (PMID 20808827, 2010). "Frataxin is thought to be the potential iron donor for Fe-S cluster biogenesis in mitochondria, and loss of functional frataxin alters heme synthesis pathway in mammalian cells and in a mouse model for the human disease, Friedreich ataxia." (PMID 20862391, 2010).
Friedreich ataxia (continued). "Friedreich ataxia (FRDA) is a relentlessly progressive neurodegenerative disorder caused by GAA·TTC repeat expansion in the first intron of the FXN gene." (PMID 19876374, 2009). "Frataxin is a highly conserved nuclear-encoded mitochondrial protein whose deficiency is the primary cause of Friedreich’s ataxia, an autosomal recessive neurodegenerative disease." (PMID 19843162, 2009). "Frataxin, the mutated gene that causes Friedreich’s ataxia (FA), encodes a protein that plays a role in mitochondrial iron homeostasis." (PMID 21814473, 2009). "Friedreich ataxia originates from a decrease in mitochondrial frataxin, which causes the death of a subset of neurons." (PMID 19158945, 2009). "In keeping with this, it has been recently shown that hydrogen peroxide scavenging rescues frataxin deficiency in a Drosophila model of Friedreich's ataxia." (PMID 19158945, 2009). "Friedreich ataxia, an autosomal recessive neurodegenerative and cardiac disease, is caused by abnormally low levels of frataxin, an essential mitochondrial protein." (PMID 18463734, 2008). "Friedreich's ataxia is a neurodegenerative condition frequently accompanied by cardiomyopathy due to a mutation in the gene frataxin, resulting in intra-mitochondrial accumulation of iron." (PMID 18397518, 2008). "Friedreich ataxia is caused by partial frataxin deficiency due to genetic mutations." (PMID 41623463, 2026). "Friedreich’s Ataxia: FRDA is an autosomal recessive neurodegenerative disease caused by expanded GAA trinucleotide repeats in the frataxin (FXN) gene located on chromosome 9q13 with an estimated prevalence of ~1 in 40,000–50,000 in populations of European ancestry." (PMID 41010490, 2025). "Friedreich ataxia is a rare neurodegenerative disorder caused by frataxin deficiency." (PMID 39797559, 2025). "Friedreich's ataxia is a neurodegenerative disorder caused by reduced frataxin levels." (PMID 38846537, 2024). "For example, a loss of frataxin, the early-acting [2Fe-2S]+ biogenesis regulator associated with Friedreich’s ataxia, has been shown to exhibit elevated levels of nuclear damage in yeast and impair DNA base excision repair activation in both prokaryotic and eukaryotic cells." (PMID 39337531, 2024). "Friedreich’s ataxia (FRDA) is a progressive neurodegenerative disease caused in almost all patients by expanded guanine–adenine–adenine (GAA) trinucleotide repeats within intron 1 of the FXN gene." (PMID 38920668, 2024). "Friedreich ataxia, the most common hereditary ataxia, is a neuro- and cardio-degenerative disorder caused, in most cases, by decreased expression of the mitochondrial protein frataxin." (PMID 36107856, 2023). "Friedreich’s ataxia (FA) is a rare neurodegenerative disease caused by the expansion of intronic trinucleotide repeat GAA from 8 to 33 repeats to >90 repeats in the FXN gene encoding frataxin protein (FXN)." (PMID 37701569, 2023). "Prominent examples of genetically caused MCM include the Barth syndrome, caused by a mutation in the TAFAZZIN (TAZ) gene, Friedreich’s ataxia, caused by a mutation in the FRATAXIN(FXN) gene and propionic acidemia, caused by a mutation in the enzyme propionyl-CoA carboxylase." (PMID 39086669, 2023). "Friedreich’s ataxia is a neurodegenerative disease caused by mutations in the frataxin gene." (PMID 36361939, 2022). "Furthermore reduced levels of FXN are responsible for causing the neurodegenerative disease of Friedreich's ataxia." (PMID 36338346, 2022). "E. coli CyaY is the homologue of human frataxin and a crucial protein for the assembly of Fe-S clusters of mitochondrial, cytoplasmic, and nuclear proteins, leading to its deficiency in the neurodegenerative disease Friedreich ataxia." (PMID 35807291, 2022).
Friedreich ataxia (continued). "It is supposed that defective expression of FXN (experimental knockout or inherited mutation leading to FXN loss in Friedreich ataxia) leading to a disturbed ISC assembly and thus accumulation of mitochondrial iron would facilitate mitochondrial lipid peroxidation and aggravate ferroptosis." (PMID 33801920, 2021). "MFRN2 levels are increased in murine models for Friedreich’s ataxia—the iron dysregulation disease associated with mutations in the mitochondrial protein frataxin (FXN)—and in patients with muscle-specific mitochondrial iron accumulation in ISC-deficiency-related human diseases." (PMID 34571846, 2021). "Friedreich’s ataxia (FRDA) is a comparatively rare autosomal recessive neurological disorder primarily caused by the homozygous expansion of a GAA trinucleotide repeat in intron 1 of the FXN gene." (PMID 34299126, 2021). "Friedreich’s ataxia (FRDA) is a comparatively rare autosomal recessive disease primarily caused by the homozygous expansion of a GAA trinucleotide repeat in intron 1 of the FXN gene." (PMID 34299126, 2021). "Friedreich’s ataxia (FRDA) is a genetic neurodegenerative disease that is caused by guanine-adenine-adenine (GAA) nucleotide repeat expansions in the first intron of the frataxin (FXN) gene." (PMID 32291635, 2020). "As an example, Friedreich’s Ataxia—one of the most common forms of inherited hereditary ataxia—is caused by the unstable expansion of a GAA trinucleotide repeat sequence within the frataxin (FXN) gene." (PMID 32499495, 2020). "Expansion of the GAA/TTC repeats in the first intron of the FXN gene causes Friedreich’s ataxia." (PMID 32821947, 2020). "Friedreich’s ataxia is caused by loss-of-function mutations in the frataxin gene (FXN)." (PMID 30833885, 2019). "Initial testing should include searching for the Friedreich ataxia-associated trinucleotide repeat expansion in the FXN gene considering the high prevalence of this mutation, its incomplete coverage through the next-generation sequencing methods, and the heterogeneous clinical phenotype." (PMID 31267374, 2019). "Due to an improved antioxidant mechanism, pioglitazone has also been proposed and trialed as a therapy for Friedreich’s ataxia, a rare neurological disorder arising from recessive genetic inheritance of a mutated Frataxin (FXN) gene on chromosome 9q13 (NCT00811681)." (PMID 31614690, 2019). "Defects in protein components of the mitochondrial ISC machinery are associated with numerous diseases, including Friedreich ataxia (defects in frataxin), myopathy (defects in ISCU or FDX2), and multiple mitochondrial dysfunction syndromes (defects in NFU1, BOLA3, ISCA2, and IBA57)." (PMID 30200358, 2018). "Loss of frataxin and this iron storage property may result in Friedreich’s Ataxia and subsequent neurodegeneration." (PMID 30428583, 2018). "Cardiomyopathy is the most common cause of death and affects 66% of patients with FA (Friedreich’s ataxia), an autosomal recessive neuro and cardio-degenerative disorder that is caused by deficient expression of the nuclear-encoded mitochondrial protein frataxin." (PMID 29875678, 2018). "Friedreich’s ataxia is caused by frataxin insufficiency leading to changes in iron metabolism that inhibits mitochondrial respiration and promotes reactive oxygen species (ROS) generation, causing mitochondrial dysfunction, oxidative stress and subsequent mitochondrial iron accumulation." (PMID 30333728, 2018). "A prospective study that evaluated the annual cost related to Friedreich’s Ataxia, a neuromuscular disorder due to a genetic mutation in the mitochondrial protein frataxin, showed that hospitalizations contributed to 21% of total direct medical costs in the UK, which is consistent with our finding." (PMID 30466460, 2018).
Friedreich ataxia (continued). "The demonstration that mesenchymal stem cell-derived factors can restore cellular homeostasis and function to frataxin-deficient cells further suggests that they may have potential therapeutic benefits for patients with Friedreich’s ataxia." (PMID 28456899, 2017). "Friedreich ataxia is caused by insufficient levels of frataxin." (PMID 28228265, 2017). "Friedreich ataxia may rarely be caused by a point mutation in FXN on one allele in combination with a typical GAA trinucleotide repeat expansion on the other allele." (PMID 28467362, 2017). "Friedreich ataxia (FRDA) is an autosomal recessive neurodegenerative mitochondrial disorder caused primarily by a homozygous GAA repeat expansion mutation within intron 1 of the frataxin gene (FXN) located on chromosome 9q21.1." (PMID 24917884, 2014). "The kinetic and aggregation stability differences of these variants may lead to the distinct functional impairments described in Friedreich’s ataxia, the neurodegenerative disease associated to frataxin functional deficiency." (PMID 25333765, 2014). "The kinetic differences observed for these frataxin mutant variants may correlate with the severity of Friedreich’s ataxia prognosis." (PMID 25333765, 2014). "Our findings suggest a direct mechanism by which FXN deficiency could cause tissue-specific pathology of Friedreich ataxia." (PMID 23082224, 2012). "Friedreich ataxia (FRDA) is an autosomal recessive neurodegenerative disorder caused by expanded GAA triplet repeats located in the first intron of the FXN gene coding for frataxin on chromosome 9." (PMID 22085827, 2011). "Friedreich ataxia (FRDA) is an autosomal recessive neurodegenerative disorder predominantly caused by a homozygous GAA repeat expansion mutation within intron 1 of the FXN gene." (PMID 21397024, 2011). "In Friedreich ataxia, mutations occur in the nuclear frataxin gene." (PMID 19718456, 2009). "Friedreich ataxia (FRDA) is a recessive condition that is typically caused by inheriting an expanded GAA repeat (usually > 500 triplets) in the FXN gene from both parents who are heterozygous carriers of the expanded (E) allele." (PMID 42262226, 2026). "Friedreich ataxia (FA) is an autosomal recessive disease caused by partial deficiency of the mitochondrial protein frataxin, with most neuropathologic changes causing ataxia limited to the infratentorial sensory system and cerebellar dentate nuclei." (PMID 40744695, 2025). "Importantly, as CyaY is the bacterial ortholog of human frataxin—implicated in Friedreich's ataxia—these insights may also inform structure‐based drug design strategies aimed at targeting frataxin‐related dysfunction." (PMID 41147201, 2025). "Friedreich Ataxia (FRDA) is an autosomal recessive neuromuscular disorder caused by a deficiency of the mitochondrial protein frataxin." (PMID 39337401, 2024). "Friedreich ataxia (FRDA) is an inherited condition caused by a GAA triplet repeat (GAA‐TR) expansion in the FXN gene." (PMID 37334854, 2023). "Friedreich ataxia (FRDA) is most commonly (>96%) caused by a GAA triplet repeat (GAA‐TR) expansion in intron 1 of the FXN gene." (PMID 37334854, 2023). "Finally, Friedreich’s ataxia/spinocerebellar degeneration is unambiguously a neurodegenerative disease with a mitochondrial etiology; the autosomal recessive genetic defect is in the FXN gene that encodes the mitochondrial iron-binding protein, frataxin." (PMID 35326500, 2022). "Friedreich ataxia (FRDA) is an autosomal recessive multisystem disorder resulting from disease-causing variants of the FXN gene." (PMID 36133907, 2022). "Friedreich ataxia (FRDA) is an autosomal recessive neurodegenerative disorder caused by deficiency of the mitochondrial protein frataxin." (PMID 35401081, 2022). "Friedreich ataxia (FRDA) is a recessive disorder resulting from relative deficiency of the mitochondrial protein frataxin." (PMID 34046211, 2021).
Friedreich ataxia (continued). "Friedreich ataxia (FRDA) is an autosomal-recessive neurodegenerative movement disorder that is caused by insufficient FRATAXIN protein." (PMID 33921346, 2021). "The first study dealt with the deletion of a pathogenic GAA repeat expansion from the frataxin (FXN) gene in cells from patients with Friedreich ataxia (FRDA, OMIM#229300))." (PMID 33921346, 2021). "Finally, HCM is the cardiac manifestation of Friedreich ataxia, an autosomal recessive neurodegenerative disease caused by mutations in frataxin (FXN) gene encoding a mitochondrial iron-binding protein involved in the synthesis of the iron-sulphur (Fe–S) clusters (ISCs)." (PMID 34072184, 2021). "Friedreich ataxia (FRDA) is a neurological disorder caused by homozygous intronic GAA expansions in the frataxin (FXN) gene." (PMID 31105516, 2019). "Friedreich ataxia (FRDA) is a progressive neurodegenerative disease with developmental features caused by a genetic deficiency of frataxin, a small, nuclear-encoded mitochondrial protein." (PMID 32714592, 2018). "Friedreich ataxia (FRDA), the most common recessive inherited ataxia, results from deficiency of frataxin, a small mitochondrial protein crucial for iron-sulphur cluster formation and ATP production." (PMID 29125827, 2017). "Friedreich ataxia (FRDA) is a severe genetic neurodegenerative disease caused by reduced expression of the mitochondrial protein frataxin." (PMID 28228265, 2017). "Deficient transcriptional initiation accounts for FXN transcriptional deficiency in the humanized mouse model of Friedreich ataxia, similar to patient-derived cells, and the mechanism underlying promoter silencing in Friedreich ataxia is widespread across multiple cell types and tissues." (PMID 26393353, 2015). "Friedreich ataxia (FRDA) is a human autosomal recessive disease caused by a GAA triplet repeat expansion in the gene encoding the frataxin, a mitochondrial protein involved in iron metabolism." (PMID 26331028, 2014). "Friedreich ataxia (FRDA) is caused by a GAA repeat expansion in the FXN gene leading to reduced expression of the mitochondrial protein frataxin." (PMID 23922695, 2013). "Friedreich ataxia (FRDA) is caused by an expansion of GAA•TTC repeats in the first intron of the frataxin (FXN) gene." (PMID 20559546, 2010). "While oxidative stress in frataxin-deficient patients with Friedreich’s ataxia may be due to the disturbed synthesis of Fe/S-clusters and mitochondrial iron deposits, it is less obvious as to how enforced overexpression of frataxin in normal cells may protect them against ROS." (PMID 19949549, 2009). "Friedreich ataxia (FRDA) is a relentlessly progressive neurodegenerative disorder caused by GAA·TTC repeat expansion within the first intron of the frataxin (FXN) gene." (PMID 19876374, 2009). "Friedreich ataxia patients are typically homozygous for an expanded GAA repeat in intron 1 of the FXN gene." (PMID 41432640, 2026). "The examples of NfL, polyQ-ATXN3, and the pons atrophy in SCA3, together with frataxin in Friedreich’s ataxia, illustrate how well-validated biomarkers can effectively bridge mechanistic insight and trial implementation." (PMID 41596528, 2026). "While the presence of GAA expansions in FXN establishes Friedreich’s ataxia as a major contributor to the ataxic presentation, the coexistence of a homozygous truncating DNAH14 variant likely modifies the clinical phenotype." (PMID 41596228, 2026). "Disease-relevant studies further demonstrate frataxin upregulation in Friedreich's ataxia and reduction of mitochondrial reactive oxygen species in C9orf72-related models." (PMID 41769702, 2026). "For example a bifunctional JQ1–polyamide compound reactivated the silenced FXN gene in Friedreich’s ataxia, illustrating the potential of precision-targeted therapeutics." (PMID 40691806, 2025).